SOST (sclerostin)
Diseases named in the same sentence as SOST in open-access papers (continued):
Sharing a sentence is not in itself a finding about the gene and the disease.
Arthritis (12 papers, 2014 to 2026). Inflammation of a joint. "Blocking sclerostin by a monoclonal antibody in human tumor necrosis factor transgenic (hTNFtg) mice model of arthritis reduces loss of systemic bone mass, periarticular bone destruction and cartilage damage, without any effect on inflammation." (PMID 33330566, 2020). "On the contrary, novel insights in TNF-dependent mouse models suggested that sclerostin blockade might be deleterious for arthritis since SOST deficiency worsened arthritis in the combined mouse model of SOST−/−/hTNFtg23." (PMID 29472591, 2018). "In an arthritis mouse model, sclerostin inhibition resulted in a decrease in the loss of bone mass." (PMID 25280749, 2014). "TNF-α, IL-17, IL-6, and DKK-1 serum levels were increased, and obestatin and sclerostin serum levels were decreased in the arthritis group compared to the control group." (PMID 32659877, 2020). "Serum sclerostin levels were 36% higher in MG group when compared with the arthritis group (P < 0.05)." (PMID 32659877, 2020). "Serum sclerostin levels were 55% lower in the arthritis group compared to the control group (P < 0.001)." (PMID 32659877, 2020). "At the time of arthritis onset, SOST and DKK1 returned to control values, but frizzled related protein 1 (SFRP1), proinflammatory cytokines, and MMPs started to increase." (PMID 29472591, 2018). "In the AIA group compared to CTRL group, expression of Wnt inhibitors SOST and DKK1 was higher at the ankle site before arthritis only (p < 0.01 each), with a trend for a SOST downregulation at day 17 (p = 0.09)." (PMID 29472591, 2018). "Recently, a paradoxical exacerbation of joint damage was described when blocking sclerostin in various arthritis models." (PMID 29472591, 2018). "In our study, sclerostin levels increased in the MG group compared to the arthritis group." (PMID 32659877, 2020). "Alternatively, the unaltered levels may be due to concurrent arthritis-associated bone degradation with erosions that is linked to increased levels of DKK-1 and SOST, which is also an integral part of SpA34." (PMID 33273664, 2020). "Targeting this Wnt inhibitor could be interesting in arthritis treatment and easier than sclerostin or DKK1 because its window of upregulation is in declared arthritis." (PMID 29472591, 2018). "So, sclerostin serum level could be proposed as a biomarker of arthritis onset." (PMID 29472591, 2018). "Chronic exposure to TNF-α promotes the upregulation of sclerostin and in a rat adjuvant-induced arthritis (AIA) model SOST and DKK-1 were overexpressed in the early stages of arthritis onset." (PMID 37887030, 2023). "Taken together, these results suggested that inhibition of bone formation was more likely to be explained by SOST in early arthritis and by SFRP1 in late arthritis, suggesting a switch in the role of Wnt inhibitors." (PMID 29472591, 2018). "We demonstrated that DKK1 and sclerostin were only upregulated before arthritis onset, while SFRP1 was only upregulated after arthritis onset." (PMID 29472591, 2018). "The low osteoblast activity correlated with sclerostin in early arthritis and SFRP1 in established arthritis." (PMID 29472591, 2018). "For this purpose, the genotyping of 552 SNPs located in gene regions of semaphorins 4b, 4d, 4f, DKK1, 2 and 3, sclerostin, OPG, RANK and RANKL was performed using Immunochip from Illumina Inc. in 268 patients from the Princesa Early Arthritis Register Longitudinal (PEARL) study." (PMID 39337893, 2024). "In the same work, sclerostin blockade with neutralizing antibody into glucose-6-phosphate isomerase (G6PI) arthritis did not improve arthritis either." (PMID 29472591, 2018). "At the ankle level, higher sclerostin concentration was observed at the protein level in the AIA group compared to CTRL group from day 6 to 10 (p < 0.05), while SFRP1 protein expression was only enhanced after arthritis onset (p < 0.01)." (PMID 29472591, 2018).
Arthritis (continued). "However, other studies in animal models of arthritis have not found that sclerostin inhibition decreases or repairs bone erosions or reduces bone loss." (PMID 33330566, 2020). "In experimental arthritis, neutralization of DKK-1 with an antibody inhibited bone erosion without affecting inflammation, whereas the neutralization of sclerostin improved systemic bone loss, but did not affect disease severity or focal bone erosions in the CIA model." (PMID 31394717, 2019).
coronary artery disease (12 papers, 2020 to 2025). "Some studies showed a positive association between serum sclerostin levels and the severity of vascular calcification and coronary artery disease, respectively." (PMID 40429697, 2025). "Our analyses confirm a causal relationship between lifelong effects of lower levels of sclerostin and an excess risk of coronary artery disease, both in meta-analysis of previous GWAS as well as in UK Biobank participants." (PMID 39537602, 2024). "By analyzing these data across more than 100,482 individuals, they identified two significant single-nucleotide polymorphisms (SNPs) (rs66838809 and rs1107748) in the SOST region, with robust evidence linking lower sclerostin levels to increased coronary artery disease risk." (PMID 40429697, 2025). "In stable coronary heart disease patients, high sclerostin increased all-cause mortality risk." (PMID 39078512, 2024). "In LURIC, higher sclerostin was associated with an increased risk of death from cardiac disease during follow‐up (hazard ratio [HR] = 1.13; 1.03, 1.23) and with severity of coronary artery disease on angiogram as reflected by Friesinger score (0.05; 0.01, 0.09)." (PMID 34738659, 2022). "Contrary to trial evidence suggesting sclerostin inhibition leads to an increased risk of CVD, sclerostin levels appear to be positively associated with coronary artery disease severity and mortality, partly explained by a relationship between higher sclerostin levels and major CVD risk factors." (PMID 34738659, 2022). "We investigated the relationship between serum sclerostin levels and adverse outcomes in elderly patients with stable coronary artery disease (SCAD) who were undergoing percutaneous coronary intervention (PCI)." (PMID 31677125, 2020). "Treating hHiPCs with BMP9 may also be critical for regulation of SOST expression and for further development of hHiPCs as a therapeutic treatment in ischemic heart disease." (PMID 39430425, 2024). "In a previous report, we revealed no evident association between sclerostin levels and coronary artery disease severity." (PMID 33800939, 2021). "Therefore, we followed a cohort of elderly stable coronary artery disease (SCAD) patients without CKD to assess the relationships between serum sclerostin levels and adverse outcomes after percutaneous coronary intervention (PCI)." (PMID 31677125, 2020).
hyperparathyroidism (12 papers, 2012 to 2025). Hyperfunction of the parathyroid glands resulting in the overproduction of parathyroid hormone. "Sclerostin levels are decreased in hyperparathyroidism, after mechanical stress, in estrogen excess and with increased corticosteroids levels." (PMID 39747949, 2025). "Even following transplantation, sclerostin eventually begins to rise in the case of hyperparathyroidism, along with FGF-23, uremic toxins, and various inflammatory cytokines." (PMID 37836411, 2023). "Patients with higher sclerostin serum levels, and therefore less severe hyperparathyroidism, had a higher BMD as measured by DXA." (PMID 31477034, 2019). "Moreover, serum levels of sclerostin are negatively correlated with the levels of serum PTH in patients with hyperparathyroidism." (PMID 34427705, 2022). "Serum sclerostin level was independently associated with pulse wave velocity only in patients without hyperparathyroidism." (PMID 32216514, 2020). "It is possible that low sclerostin is just a marker of hyperparathyroidism and plays no causative role." (PMID 31477034, 2019). "Patients with more severe hyperparathyroidism have significantly lower sclerostin." (PMID 31477034, 2019). "Antibodies to sclerostin may be used in the intervention of hyperparathyroidism." (PMID 39808360, 2025). "The results confirmed that sclerostin may play a role in hyperparathyroidism bone disease." (PMID 31477034, 2019). "For instance, lowering of sclerostin levels was demonstrated after injection of PTH and in patients with hyperparathyroidism." (PMID 23146624, 2012).
secondary hyperparathyroidism (10 papers, 2015 to 2025). Overproduction of parathyroid hormone in response to influence external to the parathyroid glands. "The aim of this study was to assess the influence of six-month cinacalcet treatment on plasma sclerostin concentration in hemodialysed patients with secondary hyperparathyroidism (sHPT)." (PMID 27846800, 2016). "Summing up, we have found that treatment with cinacalcet increases plasma sclerostin concentration in hemodialysed patients with secondary hyperparathyroidism." (PMID 27846800, 2016). "In hemodialysed patients with secondary hyperparathyroidism treatment with cinacalcet increases plasma sclerostin concentration." (PMID 27846800, 2016). "In dialysis patients, sclerostin was negatively correlated with iPTH, which may be related to the suppression of sclerostin production by osteocytes, or the decrease of bone mass in secondary hyperparathyroidism." (PMID 32458213, 2020). "Secondary hyperparathyroidism in CKD contributes to increased bone turnover by releasing calcium and phosphate, which can contribute to VC and indirectly influence FGF 23 and sclerostin regulation." (PMID 38667470, 2024). "The negative association between levels of sclerostin and iPTH concentrations, observed also in our study, may be rather explained by suppression of sclerostin production by osteocytes, or bone mass decline in secondary hyperparathyroidism." (PMID 30584645, 2019).
aortic aneurysm (9 papers, 2009 to 2025). A ruptured aneurysm located in the wall of the proximal portion of the descending aorta proceeding from the arch of the aorta. "The ability of sclerostin to antagonise transforming growth factor beta, which has been linked to aortic aneurysm development, could be of significance in an aortic protection role for this gene." (PMID 19580648, 2009). "In another human study, biopsies from aortic aneurysms contained less sclerostin protein than healthy aortic tissue." (PMID 33776907, 2021). "Sclerostin was found to inhibit angiotensin II-induced aortic aneurysm and atherosclerotic plaque formation in mice." (PMID 34441870, 2021). "Recent studies dissecting the functions of components of the sclerostin protein suggest that while the loop 3 peptide is inhibitory to the skeleton, it did not protect in an aortic aneurysm model." (PMID 36776982, 2023).
prediabetes (9 papers, 2014 to 2025). "Moreover, the SPISE index showed significant association with sclerostin only in the prediabetes group." (PMID 36004027, 2022). "SOST mRNA expression showed 2.05-fold higher in prediabetes and 3.17-fold in newly diagnosed T2D compared to healthy controls." (PMID 36004027, 2022). "Irisin inversely correlates with sclerostin levels in adults with prediabetes and with vertebral fragility fractures in post-menopausal women." (PMID 31091695, 2019). "HbA1c was presented as positively correlated with sclerostin levels in prediabetes and T2DM." (PMID 40149867, 2025). "However, this requires a few-year observational study that would allow determining whether women with a diagnosis of PCOS with normal glucose levels at the time of diagnosis, higher sclerostin levels will be a predictor of prediabetes development." (PMID 32592042, 2020). "This may be suggestive of the existence of the influence of irisin on BMI, or vice versa, in subjects with prediabetes, which should be taken into account when trying to determine the unconfounded relationship between sclerostin and adiposity in abnormal glucose tolerance status." (PMID 25276128, 2014). "Sclerostin was significantly (p<0.001) higher in T2D (465.76 (735.71)) and non-significantly elevated in prediabetes group (256.06 (299.65)) compared to healthy (251.05 (158.44))." (PMID 36004027, 2022). "In conclusion, this study demonstrates that serum sclerostin is highly correlated with serum irisin in adults with prediabetes, independent of age, gender, and BMI." (PMID 25276128, 2014).
osteosclerosis (8 papers, 2016 to 2023). Abnormally high bone density. "This study identified two kinds of new mutations in LRP5 for the first time, of which the mutation in exon 3 may cause amino acid changes in the binding site of LRP5 with SOST, an antagonist protein in Wnt pathway, resulting in more severe phenotype of osteosclerosis." (PMID 36971833, 2023). "Although osteocyte TSC1 disruption increased RANKL expression and osteoclast formation, it markedly reduced sclerostin production in bone, resulting in severe osteosclerosis with enhanced bone formation in mice." (PMID 31088250, 2019). "We found that osteocyte TSC1 disruption reduced sclerostin in bone, leading to osteosclerosis with enhanced bone formation in mice." (PMID 31088250, 2019).
periodontal disease (8 papers, 2017 to 2026). "We will now discuss in detail evidence for PSC existence and development and detail the potential use of the Sclerostin antibody and parathyroid hormone (Pth) in treatment of bone loss from periodontal disease or other craniofacial trauma." (PMID 29457146, 2017). "Sclerostin can be considered an effective therapeutic target for periodontal disease treatment, as alveolar bone volume improvement was noticed using DKK1- and Sclerostin-specific antibodies." (PMID 36902030, 2023). "Strategies to neutralize Sclerostin with antibodies have been used for the treatment of osteoporosis and periodontal disease with promising results." (PMID 34440994, 2021). "Moreover, while the role of sclerostin has been previously identified in other forms of periodontal disease, our study is the first to examine the relationship between sclerostin and AP." (PMID 40323540, 2026). "Studies investigating the GCF levels of Sclerostin and WNT-5a after periodontal therapy may further elucidate the role of these molecules in the pathogenesis of periodontal disease and evaluate their potential diagnostic and prognostic values." (PMID 34440994, 2021). "It has been suggested that anti-sclerostin medications could be developed for use in jawbone-related conditions, as regulating alveolar bone turnover may offer a therapeutic approach for managing periodontal disease and facilitating orthodontic treatment." (PMID 41294494, 2025). "The here presented literature supports the significant effects of SOST and DKK-1 in the periodontium system and periodontal diseases." (PMID 31031968, 2019).
vitamin D deficiency (8 papers, 2014 to 2026). A nutritional condition produced by a deficiency of VITAMIN D in the diet, insufficient production of vitamin D in the skin, inadequate absorption of vitamin D from the diet, or abnormal conversion of vitamin D to its bioactive metabolites. "In contrast, lower plasma levels of sclerostin are linked to vitamin D deficiency and effective phosphate control in patients undergoing HD." (PMID 38667470, 2024). "Low plasma levels of sclerostin are associated with vitamin D deficiency and good phosphates alignment in our cohort of haemodialysis patients." (PMID 30584645, 2019). "Low levels of sclerostin are associated with vitamin D deficiency and good phosphates alignment." (PMID 30584645, 2019). "We measured serum sclerostin and DKK1 in 34 patients (21 F, 13 M) aged mean (SD) 61.3 (15.6) years with vitamin D deficiency/insufficiency treated with a loading dose of vitamin D2 (300,000 IU) intramuscularly." (PMID 25548714, 2014). "Participants’ vitamin D levels were well below the normal range; however, we do not believe that vitamin D deficiency influenced bioactive sclerostin levels." (PMID 33544208, 2022). "Some earlier studies showed that high levels of the biomarkers sclerostin, osteoprotegerin, FGF or FGF-KLOTHO axis, and/or vitamin D deficiency correlated positively with AS, while others did not confirm the association of these biomarkers with AS in prevalent hemodialysis patients." (PMID 32872092, 2020). "The aim of this study was to determine changes in circulating concentrations of sclerostin and DKK1 following a loading dose of vitamin D2 (ergocalciferol) in subjects with vitamin D insufficiency." (PMID 25548714, 2014).
aortic valve calcification (7 papers, 2013 to 2025). "In summary, we identified an association between both tissue sclerostin as well as serum sclerostin with aortic valve calcification in haemodialysis patients." (PMID 24112318, 2013). "Elevated serum sclerostin and increased sclerostin mRNA expression were observed in patients with aortic valve calcification, which suggests sclerostin plays a major role in aortic valve calcification." (PMID 40559238, 2025). "On the contrary, other studies showed that elevated serum sclerostin levels were seen in patients with aortic valve calcification with increased upregulation of sclerostin mRNA." (PMID 34603797, 2021). "Elevated serum sclerostin levels were seen in patients with aortic valve calcification with increased upregulation of sclerostin mRNA." (PMID 32106499, 2020). "Here, we assessed the potential association of sclerostin with the development of coronary artery (CAC) and aortic valve calcifications (AVC) in haemodialysis (HD) patients." (PMID 24112318, 2013). "A limited number of studies investigated the role of sclerostin in aortic valve calcification." (PMID 32366042, 2020). "Higher serum sclerostin levels were observed in patients with aortic valve calcification." (PMID 32366042, 2020). "The present data are in line with recent human study results indicating an association of sclerostin expression with non-uremic aortic valve calcification." (PMID 24112318, 2013). "The same research group also compared the sclerostin expression in aortic valves, as well as serum levels in patients with and without aortic valve calcification." (PMID 32366042, 2020).
coronary artery calcification (7 papers, 2020 to 2024). Calcification of the coronary artery, used as a measure of coronary atherosclerosis, a risk factor for myocardial infarction. "In KTRs, a study showed that baseline sclerostin level was inversely associated with progression of abdominal aortic and coronary artery calcifications in a multivariable model but after adjusting for baseline calcification score, the significance was lost." (PMID 39078512, 2024). "In this study, we determined the relationships between serum sclerostin and all-cause mortality, the prevalence of cardiovascular events (CVEs), and coronary artery calcifications (CACs) in dialysis patients." (PMID 32216514, 2020). "However, although some studies have indicated an association between sclerostin and coronary artery calcification, others have argued that sclerostin levels alone do not independently increase the risk of cardiovascular events or mortality." (PMID 39767786, 2024).
fracture (7 papers, 2016 to 2026). "To confirm the clinical correlation between IL-20 and sclerostin in patients with bone fracture, we collected their serum and used ELISA to analyze their IL-20 and sclerostin." (PMID 27075747, 2016). "Osteocalcin and sclerostin were associated with hip fracture among men but did not meaningfully improve the predictive accuracy of models based on clinical risk factors alone." (PMID 41050357, 2025). "Serum IL-20 was significantly correlated with serum sclerostin in patients with bone fracture." (PMID 27075747, 2016). "Linear regression analysis showed that IL-20 was not correlated with sclerostin in healthy volunteers (r = 0.054), but positively correlated with sclerostin in patients with bone fracture (r = 0.807)." (PMID 27075747, 2016).